IL10 (interleukin 10)
Diseases named in the same sentence as IL10 in open-access papers (continued):
Sharing a sentence is not in itself a finding about the gene and the disease.
infection (continued). "Consequently, it appears that healing and resolution of infection is dependent upon effector CD8 T cells; overall activation of CD8 T cells results in lower levels of IL-13 and IL-10 as well as IFNγ produced in response to infection." (PMID 21695103, 2011). "In comparison to C57Bl/6 mice, Balb/c had delayed IFN-γ and IL-6 response, an early IL-10 that persisted to day 15 and increased by day 28 post-infection, and IL-5 levels that were significantly elevated by day 15 and remained so at day 28 post-infection." (PMID 20625554, 2010). "In WT but not in CCR2 KO mice this treatment mimicked the phenotype observed in IL-10 KO mice, killing the mice at 11±1 days post infection with increased liver injury (serum ALT levels: 810±68 versus 223±39 U/ml in anti-IL-10R and control antibody treated WT mice at day 10 post infection)." (PMID 20714353, 2010). "The low production of IL-10, however, could be due to the fact that the cytokine is said to be produced late (in vivo) following infection relatively to the innate cytokines." (PMID 20470442, 2010). "In addition, the expression of IL-10 was upregulated at eight and 26 weeks of infection relative to naïve mice." (PMID 21124899, 2010). "for example, IL10 helps to control excessive T helper 1 and CD8+ T cell responses that contribute to the immunopathology associated with infection; it also prevents the overproduction of IL4, IL5, and IL13, which can lead to severe fibrosis during the T helper 2 response." (PMID 20398313, 2010). "Since we observed a significantly increased level of IL-10 mRNA expression in the LGT on day 24 of the infection and that this cytokine is a particularly strong inhibitor of Th1-development we analyzed the possible source for the production of IL-10 in the tissue." (PMID 21079691, 2010). "However, immunosuppressive cytokines such as IL-10, IL-4 and IL-13 (anti-inflammatory effect) are significantly elevated in the later stage of the infection." (PMID 20169057, 2010). "The association between SNPs in IL10 and HIV-1 pathogenesis or infection has received considerable attention, but the importance of genotypic variation remains unclear." (PMID 20976276, 2010). "We found that IL-10−/− mice displayed enhanced clearance of infection." (PMID 21079691, 2010). "In addition, serum IL-6 levels and IL-10 levels were significantly increased in the subgroup with subsequent infection and confirmed within this cohort (data not shown)." (PMID 20090932, 2010). "Because IFN-γ gene expression is antigen-presenting cells dependent, we could hypothesize that high Il-10 levels limited its expression, though it could have been beneficial for an optimal defense against infection." (PMID 20076757, 2010). "However, we observed significantly higher levels of IL-10 by Cd36-/- macrophages over a time course of infection and over a range of multiplicities of infection with both M. marinum and BCG." (PMID 20950462, 2010). "Epithelium may have been evolved to induce proinflammatory cytokines and chemokines to recruit immune cells to the site of infection in lieu of secreting anti-inflammatory cytokine such as IL-10 to dampen the inflammation on its own." (PMID 20634980, 2010). "In support of a role for IL-10 in control of immune responses to mycobacterial infection, IL-10 mRNA is induced during experimental infection with a number of mycobacterial species, including Mtb23, and has been correlated with enhanced disease in TB patients 24–27." (PMID 20518032, 2010). "Infection with T. canis induced elevated levels of IL-4, IL-5, and IL-10 compared to control mice." (PMID 20544012, 2010). "Moreover, in individuals with DENV1 infection, the IFNα elevation appears early, followed by the induction of a pro-inflammatory cytokine IFNγ, and lastly an anti-inflammatory cytokine IL-10." (PMID 21206915, 2010).
infection (continued). "However, it is possible that IL-10 produced by other cells during infection suppresses the production or action of microbicidal factors induced in macrophages important for protection against Mtb infection." (PMID 20518032, 2010). "On the other hand, IL-10 production peaked at 24 h post-infection and subsequently returned to basal levels in WT mice, whereas FcγRIa−/− showed increased IL-10 production at 72 h post infection." (PMID 21124939, 2010). "In accordance with our findings in the lung, each cytokine/chemokine in the serum of IL-10−/− mice peaked at around 21 days after infection, suggesting that elevated levels in the sera resulted from spill-over of the immune response to the pathogen in the infected lung." (PMID 20518032, 2010). "The most significant changes correlating with the severity of infection were observed in NK cells that could result in the reduced production of pro-inflammatory IFNγ and immunosuppressive IL-10." (PMID 20226037, 2010). "Of interest, IL-10 a cytokine with strong anti-inflammatory properties and IL-6 known for its proinflammatory capacities are both elevated in stroke patients with subsequent infection." (PMID 20090932, 2010). "IL-10 may inhibit immunopathology as seen during infections with intracellular pathogens 17, 18, or curb pathogen clearance contributing to chronic infection 19–22." (PMID 20518032, 2010). "In agreement, treatment with neutralizing anti-IL-10R antibody on days 7 and 9 post infection, i.e. at the peak of IL-10 production increased the differentiation of CD11b+Ly6C+ monocytic cells towards inflammatory DCs and their subsequent maturation to Tip-DCs in the liver." (PMID 20714353, 2010). "IL-10 is a down-regulatory cytokine and plays a key role in limiting pathology by inhibiting overproduction of pro-inflammatory cytokines particularly in the chronic phase of infection." (PMID 19826490, 2009). "The number of samples which contained very low levels of IL-10 increased after infection, suggesting that an activation of T helper 2 cells leading to antibody-mediated immunity might occur." (PMID 19383119, 2009). "At 4 and 21 days post-infection IL-10 values > 5 pg/ml could be detected in 7 of 23 samples and 11 of 20 samples respectively." (PMID 19383119, 2009). "This response may be especially evident in the early phase of infection, because at this stage production of regulatory cytokines (such as IL-10) occurs at relatively low levels." (PMID 19816558, 2009). "We next tested the sensitivity of our infection protocol in gnotobiotic IL-10−/− mice." (PMID 19841748, 2009). "Thus, while IL-10 certainly impacts T cell potency following infection with wild-type- or ActA-Lm, its concentration is far below that measured after immunization with LLO-Lm-OVA." (PMID 19730694, 2009). "However, older pigs frequently had higher levels of IL-10, up to 800 pg/mL, before infection and in uninfected controls." (PMID 19860914, 2009). "Our results show that patients with severe AP had low HLA-DR expression on monocytes and high serum IL-10 concentration since the beginning of their disease, which suggest that they presented CARS and could have increased susceptibility to infection." (PMID 19442309, 2009). "Thus, it is possible that the generalized state of T cell unresponsiveness shown by FMDV-infected swine at early times post-infection is mediated by IL-10 produced by MoDCs." (PMID 19478852, 2009). "We did not detect a difference using this route of infection (data not shown), suggesting that IL-10 deficiency promotes WNV clearance at the level of the periphery as opposed to the brain." (PMID 19816558, 2009). "We subsequently measured IL-10 levels in plasma by ELISA at serial time points after infection." (PMID 19816558, 2009). "However, a role for IFN-γ in mediating IL-10 reactivation by Th1 cells during secondary infection with T. gondii has been suggested." (PMID 19646904, 2009).
infection (continued). "In addition, in that study the intensity and level of expression of the genes analyzed (IL-8, GRO-α, GRO-β, TNF-α, IL-1β, TGF-β1 and IL-10) varied according to the step of infection (3, 10 and 24 h after the addition of bacteria to the cell culture)." (PMID 21637453, 2009). "We speculate that the high IL-10 production might facilitate the formation of regulatory T cells, which could, during ongoing infection, limit pathogen-specific immune responses and thus contribute to successful colonization of the bacteria." (PMID 19834553, 2009). "The percentage of IFN-γ or IL-10 responders was similar between the infection groups." (PMID 19436745, 2009). "IL-10 may be elevated to reduce collateral tissue damage in response to a heightened proinflammatory response during the early phase of infection." (PMID 19826490, 2009). "Most important, we are able to determine that the immunological response to single FIVC infection was relatively stable - dominated by IL-10 and low CD25 and CD8 - in contrast to the dynamic and pro-inflammatory profile seen in the dual infected cats over the first month following FIVC infection." (PMID 19806226, 2009). "Increased IL-10 concentrations would be expected to decrease innate resistance to infections." (PMID 19765273, 2009). "IL-10 production by Th1 cells was also reported in animals infected with Toxoplasma gondii or with Leishmania major and shown to be required for regulation of the immune response in these infections." (PMID 19646904, 2009). "IL-10 expression by cells of the innate and adaptive immune systems reflects the importance of this cytokine in the tight regulation of the immune response, to minimize pathology during infection." (PMID 19646904, 2009). "These two cytokines, produced early in the infection could activate T cell subsets such as IL-10 and IFN-γ producing T cells." (PMID 19604415, 2009). "In order to try to dissociate these two effects of IL-10, to allow simultaneous control of infection and avoidance of pathology, we need a better understanding of the processes leading to IL-10 production, the timing of its production, and the cells that produce it." (PMID 18401464, 2008). "However, it is now becoming apparent that both adaptive (Foxp3−) regulatory T cell populations and classical T-bet expressing Th1 cells also play crucial immunoregulatory roles during infection and mediate their effects through secretion of IL-10." (PMID 18401464, 2008). "Thus, we anticipate that attempting to neutralize IL-10 in vivo during MHV68 infection will be difficult." (PMID 18389062, 2008). "Finally, two independent reports have demonstrated that blockade of the IL-10 receptor during chronic lymphocytic choriomeningitis virus infection led to clearance of the infection with enhanced IL-10 production by dendritic cells." (PMID 18389062, 2008). "Of biomedical interest, it has been suggested that the cellular source of IL-10 may vary in response to infection with different pathogens (or even genetically distinct isolates of the same pathogen), the stage of infection, or anatomical location." (PMID 18447949, 2008). "Similarly, production of IL-10 by monocytes is elevated during the infection with Chlamydia pneumoniae." (PMID 17488493, 2007). "We first tested the ability of IL-10-/- mice to clear acute LCMVARM infections." (PMID 17570849, 2007). "Previously, TLR2 KO mice were found to be less susceptible to lethal infections with Yersinia enterocolitica or Candida albicans through a mechanism that likely involved a stronger type 1 cytokine response due to diminished production of the prototypic type 2 cytokine IL10 during infection." (PMID 17676990, 2007). "The functional inactivation of CD8+ T cells in IL-10-blocked, chronically infected mice 30 days post-infection was incomplete as potent CTL (cytotoxic T lymphocytes) could be generated by in vitro re-stimulation." (PMID 17570849, 2007).
infection (continued). "Continued blockade of IL-10 throughout the course of persistent LCMVClone13 infection may result in complete viral clearance and the development of T cell immunity." (PMID 17570849, 2007). "Taken together, these results show that the IL-10 responses develop early compared to the IL-5 response and may be down-modulating immunopathological responses that occur during the early phase of infection." (PMID 18045464, 2007). "Furthermore the study showed a positive correlation between IL-10 and infection intensity which both rose to peak in children aged 11–12 years and declined thereafter." (PMID 18045464, 2007). "However, the level of viremia was significantly reduced (> 1 log) in mice receiving IL-10 blockade (1.6 × 105 ± 3.9 × 104 pfu/ml, n = 5, for LCMVClone13 infections vs. 2.3 × 104 ± 6.7 × 103 pfu/ml, n = 5, for LCMVClone13 plus anti-IL-10, p = 0.0076)." (PMID 17570849, 2007). "Interestingly, in addition to pro-inflammatory factors, infection of BEAS-2B cells with pneumococci resulted also in production of anti-inflammatory IL-10." (PMID 16834785, 2006). "al reported an up regulatory pattern of IL-10 secretion in bovine macrophages following infection with a type strain of MAP which is consistent with our findings, although the magnitude of up regulation at the protein level was much lower compared with their IL-10 levels." (PMID 16478544, 2006). "The higher proportion of early PTB in women with the IL10 ATA haplotype may also be a reflection of failure of tocolysis in the presence of infection." (PMID 15723707, 2005). "LAG3 deficiency further enhanced the production of interferon-y (IFN-γ), IL-4, and IL-10 by splenic CD4+ T cells in the initial infection phase, which may contribute to the slight suppression of E. multilocularis growth and development observed in the livers of LAG3-knockout mice." (PMID 41680821, 2026). "Importantly, intratracheal transfer of IL-10+/+ CD11b+Ly6G+Ly6C+ cells 1 day before infection to Thbs1-/- mice restored their ability to produce IL-10 in the lungs, improved host defense, and reduced lung inflammation and permeability upon infection." (PMID 41733356, 2026). "Emerging evidence suggests that CMV may impair local immune responses in the lung through immunosuppressive mechanisms, including viral IL-10–mediated polarization of monocytes toward an anti-inflammatory macrophage phenotype, potentially compromising Mtb control at the site of infection." (PMID 41050688, 2025). "Multiple previous challenge studies have shown an association between increases in IL-10 and decreased survival following ASFV infection, suggesting IL-10 production during mid or late-stage infection may dampen protective immune responses and be detrimental to host survival." (PMID 41156603, 2025). "Cytokine production following experimental infection of S. simulans has not yet been thoroughly studied, but the observed increased production of IL-10 may point toward these strains as being the causes of persistent IMIs as described in a previous study." (PMID 40757863, 2025). "Therefore, IL-10 might be protective against a severe course of infection or even the manifestation of symptoms." (PMID 40732660, 2025). "Interestingly, the changes in IL-10 levels were statistically significant in patients after two weeks of surgery, indicating that continuous infection may lead to chronic immune activation and an inability to mount an effective anti-inflammatory response." (PMID 39885417, 2025). "We hypothesize this kinetic difference may be because the immune system first employs NK cells to stimulate the immune response to infection (through early IFN-γ) but then uses NK cells to diminish the response via IL-10 secretion and return to homeostasis, thereby preventing overt pathology." (PMID 40337867, 2025).
infection (continued). "In addition to the increased participation of CD8+ T cells in the production of IFN-γ, these cells also produced other cytokines, such as IL-10 and IL-4 denoting a mixed response of the inflammatory profile after infection, predominantly directed by CD8+ T cells." (PMID 40006676, 2025). "Additionally, SNPs in genes encoding IL-10 and TNF-α, two major cytokines involved in the neonatal inflammatory response, underscore the potential for inherited variation in immune signaling to shape infection outcomes." (PMID 40927580, 2025). "Furthermore, NK cell depletion reduced serum IL-5, IL-10, and G-CSF on day 6 p.i, suggesting that NK cells may interact with other innate immune cells or endothelial cells during the early infection for regulating cytokine production." (PMID 38743761, 2024). "In addition, severe systemic stress and overwhelming microbial inoculation cause the immune system to mount a T helper type 2 (Th2) lymphocyte response that is accompanied by the secretion of IL-10 in an infection normally controlled by Th1 immunity, resulting in immunosuppression." (PMID 38682948, 2024). "The cytokines IL-17, and IL-10 can promote the proliferation of intestinal epithelial cells, production of mucus and antimicrobial peptides in intestinal epithelial cells, enhance the integrity of intestinal mucosal barrier, and prevent the pathogen invasion and infection." (PMID 39076595, 2024). "However, we could not detect any IL-4 or IL-13 cytokine release from mLN Treg cells after secondary infection while Treg cells of both genotypes released equivalent amounts of IL-10 suggesting fully functional Treg cells in RelBΔDC mice." (PMID 39443450, 2024). "Given its prominent effect on the resolution of inflammation, IL-10 production may be a consequence, rather than a cause, of the infection." (PMID 38980880, 2024). "However, in certain infections, such as viral, fungal, helminth, or bacterial infections, excessive secretion of IL-10 may hinder pathogen clearance and contribute to the development of chronic disease." (PMID 38831352, 2024). "As previously reported, IA patients, as well IM patients, may develop mould-specific immune responses predominantly polarized to the production of IL-10 at the onset of the infection, while the increase of protective T cells occurs later and is associated with a favorable outcome." (PMID 38980880, 2024). "Deficiency in sIgM impairs pathogen clearance following infection in mice and humans, and increased pathogen load will lead to the accumulation of both antigens and TLR ligands that may contribute to IL-10 production in B cells and further impede pathogen clearance." (PMID 38182585, 2024). "In addition, CD138hi regulatory plasma cells can produce IL-10 through infection and inflammation." (PMID 39611128, 2024). "Thus, targeting ASC survival factors could be a tool to affect local sIgM production and IL-10 programming in B cells at the site of inflammation or infection." (PMID 38182585, 2024). "In cases where anti-inflammatory cytokines like IL-10 are produced, they may be responsible for dampening the immune response, resulting in an inability to control parasitic growth and the progression of infection." (PMID 38455048, 2024). "Interestingly, the fact that B cells produced IL-10 post-stimulation with ABA-1 suggests that a helminth secretory product might be responsible for this effect during the infection." (PMID 39312581, 2024). "Consequently, these specific IL-10-induced alveolar macrophages may potentiate anti-S antibody-dependent enhancement of infection." (PMID 39770368, 2024). "In IL-10-tg mice, the prolonged presence of inflammatory foci and immune reactions in the liver post-infection, even in vaccinated subjects, may be attributed to a delay in chlamydia clearance, potentially below the detection threshold of current isolation techniques." (PMID 39199857, 2024).